CD8A (CD8 subunit alpha)
Diseases named in the same sentence as CD8A in open-access papers (continued):
Sharing a sentence is not in itself a finding about the gene and the disease.
tumor (continued). "A comparable result could be observed in high- and low-expression groups of CD8A, T cells CD8 (in 31 tumor types), T cells CD4 memory activated (in 26 tumor types), Macrophages M1 (in 26 tumor types), Macrophages M0 (in 24 tumor types) were also identified as differential infiltrated TIL types." (PMID 33585244, 2020). "To test this hypothesis, we depleted NK cells, CD8+ T cells, and CD4+ T cells by administering mAb PK136 (anti-NK1.1), 2.43 (anti-CD8a), and GK1.5 (anti-CD4) intraperitoneally every 3 days, respectively, before the mice were inoculated with tumor cells." (PMID 31849942, 2019). "In addition to rMVA and rMVA-CD40L, rMVA expressing profilin (rMVA-Profilin)—a protein derived from the protozoan parasite Toxoplasma gondii that is specifically recognized by mouse CD8α+ cDCs via TLR11 and TLR1224–26—was used to immunize tumor-bearing littermates." (PMID 31695037, 2019). "However, when correcting for background levels of tracer, we found a good agreement between the mean and maximum tumor-to-heart ratios and flow cytometric analysis of CD4+ and CD8a+, which makes sense from a physiological perspective when assessing different tumor types." (PMID 31754392, 2019). "To investigate the factors that may regulate the reactive efficiency of PD-L1 expression, we divided tumors into four tumor microenvironment (TME) types according to the median expression of PD-L1 and CD8A, in which TME III is CD8A-low and PD-L1-high whereas TME IV is CD8A-high and PD-L1-low." (PMID 31523194, 2019). "LUAD was the only tumor type that the z-score was negative for both CD8a and CD8b." (PMID 30926812, 2019). "Additional experiments performed in Batf3−/− knockout mice deficient for both CD103+ and CD8α+ DCs29, 43 revealed an absence of the WT1 vaccine-mediated protective responses, stressing the need for CD103+ DCs at the tumor site for induction of antitumor protective immune responses." (PMID 31384667, 2019). "As tumor-infiltrating lymphocytes (TILs) are proven to be a stable and ideal biomarker for response to PD-1 blockade immunotherapy, we evaluated the CD8A RNA levels in the HPV-positive and -negative groups based on gene profiles from the TCGA and GSE40774 cohorts." (PMID 31527697, 2019). "Furthermore, an enhanced antitumor immunological response contributed to preventing tumor recurrence, i.e., Rh2, when used as an adjuvant, was found to trigger CD4+/CD8a+ T-lymphocyte infiltration in tumor tissues and to increase T-lymphocyte cytotoxicity with cancer chemotherapeutic drugs." (PMID 31277214, 2019). "A higher CD8A expression was expected, since increased numbers of CD8+, FoxP3+, and CD4+ TILs in HPV-positive vs. HPV-negative OPSCC have been noted earlier, where in particular a higher number of CD8+TILs is linked to a better clinical outcome, irrespective of the HPV status of the tumor." (PMID 29587383, 2018). "In the absence of this mechanism, (e.g. in tumours with an activated Wnt/β-catenin pathway leading to transcriptional repression of CCL-4), impaired trafficking and function of Batf3+ dependent CD8α+ DCs and a non-inflamed tumour immunophenotype are likely results." (PMID 29157300, 2017). "Furthermore, CD8α+ DCs and CD8+ T cells increasingly infiltrate into tumor." (PMID 29312355, 2017). "Also, tumor infiltrating lymphocytes have not been measured directly, but CD8A expression has been used as a surrogate variable." (PMID 26871478, 2016). "This could explain why the decrease in CD3 (T-cells) and CD2 (T-cells, B-cells, NK cells) was more pronounced than that of CD8α (cytotoxic T-cells, NK cells, subset of DC), CD68 (macrophages, neutrophils, DC, myeloid progenitors), and CD163 (pro-tumor macrophages, M2)." (PMID 26374556, 2015). "The lipid levels of tumor-infiltrating CD8α+CD4- DCs did not vary between small and large tumors." (PMID 25886502, 2015).
tumor (continued). "Mechanistic studies showed that depletion of CD11c+ cells or lack of CD8α+ DCs attenuated the anti-tumor response generated by Flagrp170 therapy, suggesting that Flagrp170-enhanced activation of tumor-specific CTLs depends on these DCs for efficient antigen cross-presentation." (PMID 25629003, 2014). "Moreover, DCs might be fully matured by simultaneous CD40L signals, resulting in the induction of cytotoxic CD8a+ and helper CD4+ T cells and their infiltration into tumor tissues." (PMID 25013909, 2014). "CD86+ mature CD8α+ non-plasmacytoid DCs were unchanged in absolute number but their proportion in the spleen was modestly, yet significantly decreased at both ST and TT following tumor inoculation." (PMID 24575090, 2014). "Interestingly, tumor stroma samples from the good-outcome cluster overexpress a distinct set of immune-related genes, including T-cell and NK-cell markers indicative of a TH1-type immune response (granzyme A, CD52, CD247, and CD8A)." (PMID 23248625, 2012). "Moreover, tumor CD200R1 expression was strongly correlated (Spearman’s ρ > 0.5) with the expression of at least one of four commonly used T cell and myeloid infiltration markers (CD4, CD8A, CD11B and CD45) in tumors from multiple cancer types in The Cancer Genome Atlas (TCGA;)." (PMID 40428397, 2025). "Furthermore, we show that the co-expression of CD8α in CD4+ TEG011 provides additional survival signal and facilitates better T-cell persistence and infiltration in vivo, both of which are essential to sustain long-term tumor control of adoptively transferred TCR-based immunotherapy." (PMID 34759930, 2021). "Moreover, tumors that are prominently different in size does not eliminate the possibility that the observed differences in CD8a+ infiltrate could be a consequence of tumor growth rather than a response to treatment." (PMID 32086762, 2020). "Although no publicly available datasets have quantified CD8 infiltrate by IHC, we identified five series with gene expression data including CD8A (which encodes the CD8 alpha chain) in addition to The Cancer Genome Atlas (TCGA) series and a further set of 264 tumours with CD8A expression data." (PMID 31388185, 2019). "Although no increases in antigen-specific CD8α+ TILs could be detected, there was a trend for increased expression of cytotoxic genes within the tumor microenvironment as well as an increase in clonality in mice treated with DPX/mCPA/anti-PD-1 compared to those with anti-PD-1 alone or DPX/mCPA." (PMID 27777777, 2016). "Type I IFN signaling through CD8α+ DCs is crucial for development of cancer cell-specific cytotoxic T lymphocytes (CTLs) in animal models, suggesting that type I IFN induction through RLRs activated by Ads could play an important in the development of anti-tumor immunity (especially CTLs)." (PMID 28548063, 2014). "Tumour infiltrated T cells expressed TRAC, IL7R, CD8A, and were negative for naïve T cell marker CCR7." (PMID 38267611, 2024). "CD8+ T cells are effector cells in tumor immunity, when MC38 cells were implanted into mice lacking CD8+ T cells using anti-mouse CD8a antibodies, the tumor-promoting effect of exosomal ENTPD2 was eliminated (P < 0.05)." (PMID 38755598, 2024). "CD8α+ γδ T cells were apparent in the SI of WT and tumor-bearing VA and VAK mice; however, CD8α+ γδ T cells were almost absent from tumors in either model." (PMID 37309673, 2023). "Although the underlying mechanism is not clear, it is feasible to improve the anti-tumor activity and safety of CAR-T cells by optimizing the length of CD8α hinge, transmembrane domain, and linker." (PMID 35392217, 2022). "Referring to the TCGA HNSC tumor dataset, we found a positive correlation between IFN-γ-related genes (IFN-γ, CD8A, and STAT1) and PD-L1 (CD274), but not between EGF-related genes (EGFR, AKT1, and MAP2K7), which seems to support the results of this study." (PMID 35456895, 2022).
tumor (continued). "OX40 expression on pDCs has been shown to promote anti-tumor immunity, however, to our knowledge, expression of OX40 on CD8α+ cDC1s has not been previously reported." (PMID 35980974, 2022). "CD8α+/XCR1+ cDC1 was found to fail in cross-presenting to CD8+ T cells and tumor rejection in the absence of WDFY4 gene, but these mice had normal lymphoid and non-lymphoid cDC1 populations compared to BATF3-deficient mice." (PMID 34884995, 2021). "We cannot entirely exclude that superior tumor control in TEG011_CD8α may have been caused initially by more CD8 single-positive cells in the TEG011_CD8α product compared to TEG011 product, as CD4+/CD8+ ratios could not be entirely controlled in the experimental setup prior to infusion." (PMID 34759930, 2021). "Consistent with the computational analysis, IHC staining of CD8A revealed that 85% (23/27) of PSCCEs were CD8 T-cell “excluded”, in which CD8 T cells failed to infiltrate into tumor parenchyma and aggregated in the surrounding stroma instead." (PMID 34145257, 2021). "BATF3 cDC1s (CD8α+ in lymphoid tissues and CD103+ in nonlymphoid ones) were key in mediating MMP2 activity in tumors, as, in their absence, Mmp2-OE tumor growth was reduced." (PMID 34032639, 2021). "MC38 tumor-bearing mice were treated with an anti-CD8β antibody on day 4, which depletes CD8+ T cells, but not CD8α-expressing dendritic cells." (PMID 32273499, 2020). "We discovered that this was not the case, as anti-CD8α-treated and anti-NK1.1-treated enteric-glia-depleted mice exhibited reduced tumor burdens similar to that observed in the isotype-treated controls." (PMID 33282743, 2020). "Indeed, co-transfer of WT host-type spleen DCs (which contain CD8α+ DCs) and T cells into allogeneic B2m−/− recipients, which are functionally deficient in antigen presentation, induced a significant CD8+ T cell-mediated GVL response, leading to prolonged survival of recipients without tumor." (PMID 30774630, 2019). "FLT-3 ligand-induced tumor mice resulted in an increase in all splenic cDC resident and migratory subsets negative for CXCR4, with 30.4% of CXCR4− cDCs being CD8α+, 59.5% were CD11b+, and 42.2% were CD103+." (PMID 30489627, 2018). "Indeed, αCD8A depleted CD8+ T cells unanimously in TME, TDLN and spleen, but it did not abrogate NLRP-eco anti-tumor capacity." (PMID 40087771, 2025). "We then discerned that significant positive correlations between TIMP1 and CD8A were confined to instances where TIMP1 was expressed in the immune segment (highlighted in red), rather than with TIMP1 expression in the tumor segment (depicted in green) (lower correlation panels)." (PMID 38777826, 2024). "In this tumor analysis, DSP-0509 monotherapy did not increase Cd8a or Gzmb expression." (PMID 39054418, 2024). "Subsequently, we sorted separate sets of CD4+ TEG011 cells that co-expressed either exogenous CD8αα (CD4+CD8α+) or CD8αβ (CD4+CD8αβ+) as well as TEG011 cells expressing only endogenous CD4 and CD8 as negative and positive controls for tumor recognition, respectively." (PMID 34759930, 2021). "In contrast, in the OV2944-HM-1 model, which was insensitive to anti-PD-L1 mAb treatment, expression of CXCR3 ligands in the tumor was lower than that in the FM3A model and we confirmed that anti-PD-L1 mAb treatment increased the number of CD69+CD8α+ T cells in lymph nodes but not in tumors." (PMID 34230534, 2021). "Furthermore, T cell-related genes such as CD8A/B, PD-L1, LAG3 and IFNG were not more highly expressed in anti-PD-1-responsive tumours." (PMID 34885021, 2021). "However, m1928z-CD40L CAR T cell treatment did specifically lead to an increase in the tumor-resident CD103+ cDC1 population, whereas lymphoid CD8α+ cDC1s were not elevated." (PMID 33268774, 2020). "The exact T cell infiltration kinetics indeed depend on murine tumor model and XRT dose schedule and it is plausible that our dosing regimen or the timing of PET imaging was not optimal to detect systemic changes in CD8a+ numbers." (PMID 32086762, 2020).
tumor (continued). "FAP intensity, but not CD8a density, acted as an independent prognostic marker in multivariable analyses also, including CD8a density, age, stage, MMR status, adjuvant treatment, location, tumor differentiation and gender." (PMID 33153037, 2020). "Both immunostimulatory CD8α + and CD8α- DC subsets were increased, whereas expression of activation markers CD40, CD70, CD86, and of MHC Class I molecules in either subsets of tumor infiltrating DCs were not altered by CD1d blockade." (PMID 25349699, 2014).
cancer (10,290 papers, 1990 to 2026). A tumor composed of atypical neoplastic, often pleomorphic cells that invade other tissues. "One potential mechanism is the induction of cell death associated with increased ROS production in cancer cells and the induction of cytotoxic activity by reactivating immune cells, particularly CD8α+ T cells." (PMID 40076581, 2025). "In silico analysis of The Cancer Genome Atlas (TCGA) data highlighted a unique association in HCC that high LSD1 and low CD8A levels coincided with an elevated risk of death among all 41 cancer types." (PMID 40356247, 2025). "Consistently, we also observed a notable inverse association between the expression of C5aR and CD8A in cancer patients." (PMID 38098230, 2024). "Such an active immune state of the TME defined by the CD8A to CSF-1 expression ratio is associated with a positive response to αPD-1/αPD-L1 therapies in patients with cancer." (PMID 35292516, 2022). "We aimed to uncover the underlying mechanisms and predictive accuracy of CD8A, thereby laying the groundwork for future cancer management and research." (PMID 36035168, 2022). "In advanced cancer patients treated with immunotherapy, low CD8A expression was associated with immunotherapeutic failure and poor survival outcomes." (PMID 36230788, 2022). "Our findings denoted the underlying mechanics of CD8A in reflecting the T-cell-inflamed profiles, which has potential as a biomarker in cancer diagnosis, prognosis, and therapeutic responses." (PMID 36035168, 2022). "Next, we investigated genomic alteration profiles of CD8A in cancer, and results revealed that mutation and amplification were the most common alteration patterns." (PMID 36035168, 2022). "CD274 and CD8A can reflect PD-L1 and PD-1 expression values, suggesting that Ms are associated with novel immunotherapy for some cancers." (PMID 35265626, 2022). "Based on the pan-cancer cohorts of the Cancer Genome Atlas (TCGA) database, our results demonstrated the distinctive CD8A expression patterns in cancer tissues and its close associations with the prognosis and disease stage of cancer." (PMID 36035168, 2022). "We found that the CD8A gene is positively associated with a variety of cancers, a result also confirmed by other research groups." (PMID 36505419, 2022). "Among the many F9 associated genes overexpressed in SMC vs. TCGA were CD8A, a marker of the cytotoxic T lymphocytes and PD-L1, an important mediator of immune checkpoint and target of multiple cancer immunotherapies." (PMID 29713003, 2018). "To evaluate the functionality of NK-CARs, we used CD19 single-chain variable fragment (scFv) FMC63 with a Myc-tag as the extracellular (EC) domain to target CD19-positive cancer cells, which is linked to the CD8α hinge (H), transmembrane (TM) and cytoplasmic signaling domain (CYP)." (PMID 40045373, 2025). "Moreover, in advanced cancer patients receiving immunotherapy, it is noted that low CD8A expression showed an association with poor immunotherapy effect and survival." (PMID 37325556, 2023). "Our results showed that low CD8A expression was associated with poor survival outcomes among cancer patients treated with immunotherapy, and patients in the high CD8A expression group had a higher percentage of PR/CR than those in the low CD8A expression group." (PMID 36230788, 2022). "In some cancers, PD-L1 is even more significantly associated with favorable outcome than CD8A." (PMID 31523194, 2019). "As a result, we may be able to elucidate CD8A’s significant potential as a response predictor to various antitumor therapies, which may aid in understanding the mechanisms underlying drug resistance and survival outcome differences in certain cancer patients." (PMID 36035168, 2022). "Strikingly, MBNL1 showed a significant positive correlation for T cell infiltration (based on CD8A expression) for 27 of 29 analyzed TCGA cancer types." (PMID 40305509, 2025).